PPAT (phosphoribosyl pyrophosphate amidotransferase)
Diseases named in the same sentence as PPAT in open-access papers (continued):
Sharing a sentence is not in itself a finding about the gene and the disease.
cancer (25 papers, 2015 to 2025). A tumor composed of atypical neoplastic, often pleomorphic cells that invade other tissues. "Importantly, a recent study implicated the up-regulation of PPAT in the malignant progression of many cancer types." (PMID 40208903, 2025). "In addition, meta-analyses of human cancers have shown that PPAT is most strongly associated with malignancy among the metabolic enzymes, particularly prominent in neuroendocrine cancers, including small cell lung cancer (SCLC)." (PMID 36408139, 2022). "Among the identified factors, PPAT may be one of the most promising targets, given its substantial contribution to the nitrogen shift from glutamine as well as its high association with prognosis in many cancer types." (PMID 32184390, 2020). "Pan-cancer analysis revealed that purine biosynthesis enzymes, such as PPAT and PAICS, were significantly upregulated in LUAD and LUSC, underscoring the critical role of purine metabolism in NSCLC." (PMID 40699765, 2025). "Studies have shown that the expression of PPAT is directly regulated by the proto-oncogene c-Myc, and its abnormal high expression can promote the rapid proliferation of cancer cells by accelerating the production of purine nucleotides." (PMID 41394399, 2025). "PPAT catalyzes the initial committed step of de novo purine nucleotide biosynthesis, implying that targeting PPAT can serve as a successful cancer strategy." (PMID 37999212, 2023). "This compound, discovered by LIGHTHOUSE solely on the basis of the PPAT amino acid sequence, is thus a potential lead compound for the development of new therapeutics targeted to a variety of cancers." (PMID 36246574, 2022). "A meta-analysis of most human cancers (considered by these authors) revealed a high ratio of PPAT/Glutaminase 1 (GLS1), which correlated with cancer prognosis." (PMID 33854965, 2021). "We therefore next applied immunoblot analysis to measure the abundance of metabolic enzymes including GLS1 and PPAT in 118 cancer cell lines originating from a variety of human tissues." (PMID 32184390, 2020). "Here, the authors show that glutamine nitrogen is also affected in cancer and demonstrate that glutaminase 1 and phosphoribosyl pyrophosphate amidotransferase are the key enzymes that control this metabolic switch." (PMID 32184390, 2020). "Although glutamine is directly subjected to catabolic and anabolic reactions by GLS1 and PPAT, respectively, the relation between the fate of glutamine and cancer malignancy has remained to be fully elucidated." (PMID 32184390, 2020). "Glutamine plays a critical role in cancer metabolism, and serves as a co-substrate for PPAT and PFAS." (PMID 26140362, 2015). "As an orthogonal analysis of the relationship between purine metabolism and the ETC, we used the Cancer Dependency Map (DepMap) to identify co-essential genes with PPAT32, which encodes Phosphoribosyl Pyrophosphate Amidotransferase, the rate limiting enzyme of the de novo purine synthesis pathway." (PMID 38876105, 2024). "This influence might specifically alter the glycolysis process involving PAICS and PPAT, thereby impacting the overall metabolic profile and behavior of cancer cells." (PMID 38139175, 2023). "PPAT could be used as one of the most promising therapeutic targets for its close correlation with patients' prognoses in many cancer types." (PMID 36861063, 2023). "PPAT catalyses the first committed step of de novo purine nucleotide biosynthesis, suggesting that targeting PPAT might be a promising cancer strategy." (PMID 33407546, 2021). "Notably, a meta-analysis of multiple cancer cohorts identified elevated expression levels of PPAT as a strong predictor of tumor malignancy, altering nitrogen metabolism to favor purine biosynthesis for cell proliferation." (PMID 34685583, 2021). "Interventions to reduce the PPAT/GLS1 ratio suppresses tumor growth of many types of cancer." (PMID 32184390, 2020). "Consistently, PPAT silencing repressed cancer cell proliferation." (PMID 33520699, 2020).
cancer (continued). "Therefore, elucidating the regulatory mechanism of PPAT activity will not only enhance our understanding of purine metabolism in a biological context but also contribute to advances in basic and therapeutic research on cancer." (PMID 40208903, 2025). "PAICS, along with PPAT (phosphoribosyl pyrophosphate amidotransferase), another enzyme in the purine biosynthesis pathway, are thought to be key drivers in the metabolic reorientation of cancer cells towards aerobic glycolysis, commonly known as the Warburg Effect." (PMID 38139175, 2023). "Some enzymes in this pathway (PPAT, PAICS) are expressed at higher levels in specific types of cancer." (PMID 37628755, 2023). "Previous studies indicated that PPAT and PAICS were highly expressed in various cancers at advanced stages and involved in progression, which led to proposals for PPAT and PAICS as therapeutic inhibition targets." (PMID 34070461, 2021). "Among them, four genes (PPAT, ATIC, IMPDH1, and RRM2) belong to the purine de novo biosynthesis pathway which is indispensable for cancer cell proliferation." (PMID 33520699, 2020). "Consistent with RNA expression, immunoblot analyses of PPAT, PAICS and PKM2 showed increased expression in cancer tissues compared to normal lung." (PMID 26140362, 2015). "Given that PPAT and PNP are highly expressed in aggressive cancers, their elevated levels in PTB may reflect an increased demand for nucleotides in response to stress." (PMID 40825832, 2025). "Cancer cells coordinate a shift from glutaminolysis to de novo nucleotide biosynthesis via metabolic reprogramming coordinated by GLS1 and phosphoribosyl pyrophosphate amidotransferase (PPAT), the enzyme that initiates the rate-limiting step in de novo purine nucleotide biosynthesis." (PMID 33946927, 2021). "To investigate the generalizability of the notion that the balance between PPAT and GLS1 is deterministic for proliferation of human cancer cell lines, we examined the effects of overexpression of these enzymes in A549 and HeLa cells, which preferentially rely on pyruvate for TCA anaplerosis." (PMID 32184390, 2020). "Collectively, our data indicated that modulation of glutamine fate might be of therapeutic value for many types of cancer, with the potential antitumor effect possibly being predictable on the basis of the endogenous expression levels of GLS1 and PPAT." (PMID 32184390, 2020). "Glutamine also serves as a substrate of PPAT and FGAMS for catalyzing PRA and FGAM formation in the de novo purine biosynthesis, which may partially explain why glutamine is one of the most highly consumed nutrient by cancer cells." (PMID 30105018, 2018).
tumor (25 papers, 1992 to 2025). "Importantly, supplementing the growth medium with hypoxanthine (HX), a key nucleobase in the purine salvage pathway, almost fully restored impaired tumor cell proliferation caused by PPAT knockout." (PMID 40097378, 2025). "As a core regulator of glutamine metabolism, PPAT (Phosphoribosyl pyrophosphate Amido transferase) plays an important role in tumor development by mediating the purine nucleotide biosynthesis pathway." (PMID 41394399, 2025). "A subsequent cell proliferation assay revealed a marked tumor cell growth inhibition following PPAT knockout." (PMID 40097378, 2025). "Remarkably, our results demonstrated that depletion of PPAT completely abolished HB tumor growth in vivo." (PMID 40097378, 2025). "PPAT was found essential for HB progression as evidenced by enhanced cell proliferation, cell migration and tumor progression." (PMID 40097378, 2025). "Remarkably, overexpressing PPAT in either HuH6 or HepG2 cells significantly boosted tumor cell growth." (PMID 40097378, 2025). "Consistently, we also observed increased PPAT expression in HB tumor samples in two independently published HB datasets (GSE132219 and GSE104766)." (PMID 40097378, 2025). "Heightened GLS1 activity hinders tumor growth, whereas increased PPAT activity supports cell proliferation." (PMID 38255314, 2024). "The expression of PPAT was significantly higher in the tumor group compared to the normal group, which was statistically significant." (PMID 36711025, 2023). "The high ratio of phosphoribosyl pyrophosphate amidotransferase (PPAT) to glutaminase (GLS1) enhances tumor growth including SCLC." (PMID 36597133, 2023). "In contrast, depletion of PPAT in both cell lines inhibited proliferation in 2-D and 3-D culture as well as tumor formation in nude mice." (PMID 32184390, 2020). "Notably, the rate-limiting DNPS enzyme PPAT was markedly upregulated and was found essential for HB tumor cell proliferation, migration and progression, thereby displaying a pro-tumorigenic role in HB." (PMID 40097378, 2025). "Restoring GLS1 expression and/or downregulating PPAT enzyme might be effective in redirecting glutamine metabolism and inhibiting tumor growth." (PMID 38255314, 2024). "In the present study, we identified five genes (LDHA, PPAT, BFSP1, NR0B1, and PFKFB4) associated with the tumour immune microenvironment in HCC patient cohorts that may be applied as potential biomarkers of HCC immunotherapy outcome." (PMID 33407546, 2021). "Indeed, RNA-sequencing data for SCLC patients (GSE60052) revealed that PPAT expression was greater in tumor than in normal tissue, whereas GLS1 expression was lower in tumor than in normal tissue." (PMID 32184390, 2020). "Guanosine accelerated the malignant progression of ICC inhibition of purine metabolism-related genes, PPAT and IMPDH2, suppressed the malignant phenotype in HCCC-9810 cells, and inhibited tumor growth." (PMID 36711025, 2023). "Using RT‐PCR, we observed that AZD‐6482 significantly inhibited expression of three tumor survival markers, LDHA, PPAT, and SMS (t‐test, p < 0.05)." (PMID 35676822, 2023). "Lastly, the wet-lab qRT-PCR experiments compared the mRNA expressions of PPAT, ATIC, IMPDH1, DCK, and RRM2 in between 10 pairs of human primary HCC tissues and neighboring non-tumor liver tissues." (PMID 33520699, 2020). "We established glutamine-mediated induction of PPAT and PAICS as an important metabolic event for increased expression of these genes during lung oncogenesis, which in turn enhances tumor-specific pyruvate kinase activity." (PMID 26140362, 2015). "The hyperactive mutant β-catenin transcriptionally stimulated PPAT expression, thereby enhancing DNPS flux to promote HB tumor progression, which could be efficiently targeted by the specific DNPS inhibitor LTX." (PMID 40097378, 2025).
tumor (continued). "According to our analyses, ADM exhibited positive correlation with metabolic reprogramming, particularly in purine (PPAT, GMPS, RRM1, and RRM2) and pyrimidine (CAD and UMPS) metabolic pathways, suggested that it played an important role in tumor cell metabolic adaptation." (PMID 40547013, 2025). "A significant reduction both in tumor growth and weight was observed in both PPAT (respectively) and PAICS (respectively) knockdowns compared to the control cells, demonstrating that PPAT and PAICS play essential role in lung tumor growth in vivo." (PMID 26140362, 2015). "A549 cells with stable knockdown of PPAT or PAICS showed reduction in CAM tumor growth compared to cells with non-targeting shRNA controls (respectively)." (PMID 26140362, 2015). "Note that in the absence of tumor formation at day 3, the expression of PPAT, IMPDH1, IMPDH2, DHODH but not PAICS are all statistically significantly elevated with MYC induction." (PMID 18628958, 2008). "Together, these various data suggested that a reduced activity of PPAT inhibits tumor growth, and they were consistent with the notion that the balance between GLS1 and PPAT governs the metabolism of carbon and nitrogen derived from glutamine and thereby controls cell proliferation and tumor growth." (PMID 32184390, 2020).
adenocarcinoma (2 papers, 2015 to 2021). A common cancer characterized by the presence of malignant glandular cells. "Furthermore, our analysis showed that PPAT and PAICS are highly expressed in the solid type of adenocarcinoma." (PMID 26140362, 2015).
gastrointestinal tumours (1 paper, 2022). "PPAT was also known to be involved in the amino acid metabolism and mutate in gastrointestinal tumours." (PMID 35685372, 2022).
PPAT also shares sentences with these, for which no sentence is quoted: hepatocellular carcinoma (3 papers); diabetes (2); gastric cancer (2); hospital-acquired infections (2); neuroblastoma (2); Obesity (2); progeria (2); xeroderma pigmentosum (2); Alzheimer disease (1); bladder tumour (1); breast tumours (1); cardiovascular diseases (1); cerebral infarction (1); cholangiocarcinoma (1); COVID-19 (1); degenerative disease (1); ductal carcinomas (1); folate deficiency (1); glioma (1); hepatoblastoma (1); infection (1); intrahepatic cholangiocarcinoma (1); large cell lung carcinoma (1); lymphoma (1); malaria (1); metastatic tumor (1); musculoskeletal diseases (1); oligodendroglial neoplasms (1); oral squamous cell carcinoma (1); pancreatic cancer (1).
A further 3 diseases each share a sentence with PPAT in 1 paper.